NEGR1 (neuronal growth regulator 1)
Diseases named in the same sentence as NEGR1 in open-access papers (continued):
Sharing a sentence is not in itself a finding about the gene and the disease.
tumor (19 papers, 2015 to 2025). "Low levels of NEGR1 were associated with tumour recurrence, while low expression of miR-21-5p significantly stimulated apoptosis and reduced cell migration in vitro." (PMID 39057097, 2024). "miR-576-5p was overexpressed in tumour cells, with a role in promoting the malignant properties of tumorigenic cells by regulating NEGR1 expression." (PMID 39057097, 2024). "Neuronal growth regulator 1 (NEGR1) was originally identified as a differentially expressed gene in human tumor biopsies that is commonly downregulated in many cancer tissues including the colon, ovary, and stomach." (PMID 37187893, 2023). "The protein expression of NEGR1 was lower in tumor parts compared with normal parts and its expression was correlated negatively in staging from the CPTAC cohort." (PMID 34202934, 2021). "We were surprised to observe 100% of our tumor samples displaying a deletion immediately upstream of the Neuronal Growth Regulator 1 (NEGR1) gene." (PMID 32375678, 2020). "Among them, neuronal growth regulator 1 (NEGR1) and basic helix-loop-helix family member e22 (BHLHE22) are crucial transcription factors associated with neuron development, which as tumor suppressors were downregulated in the subtype 1 of ESCC." (PMID 27966444, 2016). "Furthermore, the mRNA expression of NEGR1 was lower in tumor parts compared with normal parts, and its expression was correlated negatively in nodal metastasis and staging from TCGA (right two panels)." (PMID 34202934, 2021). "Given that adhesion properties are crucial in tumor cell migration and invasion during metastasis, NEGR1 may play a role in malignant transformation by regulating intercellular and cell-to-matrix interactions." (PMID 34070617, 2021). "Based on this finding, it is therefore difficult to support the notion that NEGR1 might be involved in tumor etiology in the context of pHGG, and possibly other cancers as well." (PMID 32375678, 2020). "The Negr1-derived peptide described here demonstrated the capability to degrade ALK and slow tumor progression in vitro and in vivo." (PMID 37765276, 2023). "In terms of tumor stage, differential expression of NEGR1, NTNG1, XPNPEP2, CD109, and PRND had statistical significance in all tumor stage groups." (PMID 34737762, 2021). "In designing a therapeutic strategy to enhance an IgLON family TSG activity in tumor cells, two options have been considered: (a) whole-protein replacement therapy for OPCML or (b) a peptide fragment derived from the first Ig domain for NEGR1." (PMID 40699804, 2025). "This study showed that NEGR1 was related to the overall survival of THCA patients, and a low NEGR1 expression may drive tumor progression by abnormal cell adhesion." (PMID 34737762, 2021).
cancer (17 papers, 2015 to 2025). A tumor composed of atypical neoplastic, often pleomorphic cells that invade other tissues. "Our data revealed that miR-150-5p upregulates NEGR1, a neuronal growth regulator whose loss enhances migration and invasion in various cancers." (PMID 41477124, 2025). "The cell adhesion molecule encoded by NEGR1 has also been reported to be down-regulated in many human cancers." (PMID 32375678, 2020). "The IgLON family member Negr1 has been identified as a commonly downregulated gene in many human cancer tissues." (PMID 37765276, 2023). "Negr1 is downregulated in various human cancers, including colon, liver, lung, ovary, stomach, and pancreas tumors." (PMID 37765276, 2023). "Intriguingly, the upstream NEGR1 CNV deletion was homozygous in ~ 40% of individuals in the non-cancer population." (PMID 32375678, 2020). "Deletions in many of our hotspot genes (e.g., NRXN1, PDE4D, WWOX, LSAMP, and NEGR1) are also found in numerous cancers where they likely represent the effects of perturbed replication and transcription." (PMID 25373142, 2015). "Accordingly, we observed that the Negr1 protein is downregulated in cancer-derived cell lines." (PMID 37765276, 2023). "The Negr1 protein level was below detection in all samples derived from cancer lines." (PMID 37765276, 2023). "We found high-frequency deletions upstream of the NEGR1 locus in pHGG and non-cancer cohorts." (PMID 32375678, 2020). "However, our analyses of non-cancer populations clearly show that the NEGR1 promoter deletion is present in a majority of individuals in the general population." (PMID 32375678, 2020). "However, analysis of genomic information from multiple non-cancer cohorts showed that both the NEGR1 promoter deletion and the BTNL3–8 deletion were CNVs occurring at high frequencies in the general population." (PMID 32375678, 2020). "Thus, we assessed whether ectopic treatment with the Negr1 protein might modulate cancer cell growth." (PMID 37765276, 2023). "Conversely, the expression levels of LEPR, POMC, MC4R, and NEGR1 in two (GBM and PAAD), two (CHOL and LUSC), four (LUAD, LUSC, PCPG, and THCA), and two (CHOL and PCPG) types of cancer were higher than those of the corresponding normal tissues, respectively." (PMID 33299884, 2020). "According to the top 25 over/underexpressed genes for each type of cancer, LEP and NEGR1 were found to be extremely important in the occurrence of BRCA and BLCA cancer." (PMID 33299884, 2020). "Among the module genes, BUB1, GATM, PLCE1, NEGR1, PTGER3 and SH3RF2 were differentially expressed in three or more cancer tissues." (PMID 28694494, 2017).
neurodevelopmental disorder (3 papers, 2023 to 2025). A behavioral and cognitive disorder with onset during the developmental period that involves impaired or aberrant development of intellectual, motor, or social functions. "Potentially damaging CNVs (pdCNVs) provided support to the involvement of inherited variants in PHF3, NEGR1, TIAM1 and HOMER1 in neurodevelopmental disorders (NDD), although mostly acting as susceptibility factors with incomplete penetrance." (PMID 37961520, 2023).
metabolic disorders (2 papers, 2021 to 2022). "The 1p31.1 locus harbours the neuronal growth regulator 1 (NEGR1) gene, which has previously been associated with psychiatric, behavioural, nutritional and metabolic disorders." (PMID 36297114, 2022).
neurodegenerative disease (2 papers, 2018 to 2023). A disorder of the central nervous system characterized by gradual and progressive loss of neural tissue and neurologic function. "The overexpression of NEGR1 gene prevents synaptogenesis leading to autoimmune or neurodegenerative diseases." (PMID 29503661, 2018).
neurological diseases (2 papers, 2015 to 2020). "Given its possible implication with several neurological disorders, clarifying the function of Negr1 and the underlying biological pathways linked to neuronal function may provide a potential target for future therapeutic intervention." (PMID 26793057, 2015). "Both NLGN1 and NEGR1 are involved in mammalian nerve development, and they may induce neurological diseases." (PMID 33391332, 2020).
brain disorder (1 paper, 2017). A disease affecting the brain or part of the brain. "Further suggestive of the role NEGR1 has in brain disorders, NEGR1 is also elevated in the CSF of bipolar and depressed patients." (PMID 29249937, 2017).
infection (1 paper, 2015). The state of being infected such as from the introduction of a foreign agent such as serum, vaccine, antigenic substance or organism. "Biochemical and imaging analysis showed that the titer of infection influenced the extent of both infection efficiency and Negr1 protein reduction." (PMID 26793057, 2015). "The magnitude of the effect was, however, lower than that reported upon high viral titer infection, i.e., upon massive and general down regulation of Negr1 protein levels in the cultured neurons." (PMID 26793057, 2015). "Indeed, we also observed a clear morphological defect upon infection with low titer of Negr1 siRNA viruses." (PMID 26793057, 2015).
NEGR1 also shares sentences with these, for which no sentence is quoted: Alzheimer disease (3 papers); mood disorder (3); endometriosis (2); obesity syndromes (2); Seizure (2); anaplastic thyroid carcinoma (1); asthma (1); atrial fibrillation (1); bacterial diseases (1); behavior disorders (1); bladder cancer (1); breast carcinoma (1); cardiovascular disease (1); cognitive disorder (1); ductal carcinoma in-situ (1); gastric cancer (1); Huntington disease (1); invasive breast carcinoma (1); language delays (1); migraine (1); morbid obesity (1); Onset (1); osteosarcoma (1); pancreatic cancers (1); prostate carcinoma (1); syndromic (1); Wilms tumor (1).